EGFR (epidermal growth factor receptor)
Diseases named in the same sentence as EGFR in open-access papers (continued):
Sharing a sentence is not in itself a finding about the gene and the disease.
lung adenocarcinoma (continued). "At the same time, in the part of network pharmacology, we found that an important signaling pathway for the intervention of SD on lung adenocarcinoma was EGFR signaling pathway." (PMID 35190747, 2022). "Patients with EGFR-mutant lung adenocarcinoma who received BM radiotherapy between November 2011 and April 2021 were included in this retrospective study." (PMID 35241046, 2022). "Among patients with lung adenocarcinomas, EGFR and KRAS were the highest discrepancy genes in the different racial groups (P<0.001)." (PMID 36248982, 2022). "Epidermal growth factor receptor (EGFR) is the most common driver gene mutation of NSCLC, with approximately 35% of Asian patients and 60% of patients with lung adenocarcinomas." (PMID 36034789, 2022). "The EGFR T790M mutation is considered a cause of acquired resistance to EGFR-TKI therapy and is found in approximately 60% of patients with lung adenocarcinoma treated with EGFR-TKIs." (PMID 34643820, 2022). "In our previous studies, a PET/CT radiomics model was developed to predict epidermal growth factor receptor (EGFR) mutation and anaplastic lymphoma kinase (ALK) rearrangement status in lung adenocarcinoma." (PMID 35445899, 2022). "RB1 inactivation was believed to be responsible for the transformation of EGFRm lung adenocarcinoma to SCLC following EGFR TKIs, similar to de-novo SCLC." (PMID 35268520, 2022). "In this nonrandomized, phase II, open-label, 3-arm prospective proof-of-concept pilot study, 48 patients with metastatic EGFR-mutant lung adenocarcinoma (LUAD) received osimertinib 80 mg daily." (PMID 35156036, 2022). "Similar findings were detected in EGFR-mutant lung adenocarcinoma preclinical models and individuals with BRAF V600E lung adenocarcinoma." (PMID 36230484, 2022). "Here, we aimed to examine ERα, Erβ, and GPER1 expressions, and to analyze their roles in the mechanism of EGFR-TKIs resistance in lung adenocarcinoma." (PMID 35664735, 2022). "A multicenter prospective study showed that 29 of 295 (9.8%) EGFR-wild type patients with lung adenocarcinoma were positive for EML4-ALK translocation, which occurred more frequently in patients younger than 65 years." (PMID 35806042, 2022). "Biomarkers that predict the efficacy of first-line tyrosine kinase inhibitors (TKIs) are pivotal in epidermal growth factor receptor (EGFR) mutant advanced lung adenocarcinoma." (PMID 36052262, 2022). "As compared with wild type lung adenocarcinoma, EGFR-mutant and HER2-mutant patients had similarly low PD-L1 and strong PD-L1 positive rates." (PMID 35980949, 2022). "Our combined model showed good performance in predicting EGFR molecular subtypes in patients with lung adenocarcinoma." (PMID 35574401, 2022). "Genomic data analyses evidenced that EGFR and KRAS mutations, the most common aberrations in lung adenocarcinoma, are extremely rare in pure SCC, while alterations in the FGFR kinase family, PIK3CA, CDKN2A and RB1 pathways are common." (PMID 35743191, 2022). "Our previous study reported that lung adenocarcinoma with different localizations of EGFR proteins responds favorably to platinum-based chemotherapy." (PMID 36358752, 2022). "We performed a single-center retrospective analysis evaluating clinical outcomes of a cohort of 178 patients with EGFR-mutant lung adenocarcinoma (LUAD) post-EGFR TKI systemic therapy in patients who were treated at MD Anderson Cancer Center." (PMID 35884533, 2022). "The transcriptional complex of activated YAP and TEAD binds to the PD-L1 promoter in EGFR-TKI-resistant lung adenocarcinoma cell lines." (PMID 36294681, 2022). "In this study, IMAs had a low somatic mutation burden, but they did have a heterogeneous genomic landscape, which was similar to Asian EGFR-mutant lung adenocarcinomas." (PMID 34290355, 2022). "CT-based radiomics has predicted the mutation status in patients with CRC and in lung adenocarcinoma patients for KRAS/BRAF and EGFR, respectively." (PMID 36612061, 2022).
lung adenocarcinoma (continued). "In patients with EGFR-mutant advanced lung adenocarcinoma with concomitant non-EGFR genetic alterations, combination of TKIs and chemotherapy was significantly superior to EGFR-TKIs monotherapy, which should be the preferred treatment option." (PMID 36172729, 2022). "Apart from EGFR and KRAS, the proto-oncogene B-Raf (BRAF) gene that encodes a serine/threonine kinase was identified in 3% (18/687) of western patients with lung adenocarcinomas but only in 0.5% (25/5,125) of Asian patients." (PMID 36059824, 2022). "All six patients were diagnosed with lung adenocarcinoma and were wild‐type for EGFR, KRAS and ALK‐translocations." (PMID 36251951, 2022). "Prostate and EGFR-mutant lung adenocarcinoma initially respond to the first generation of antiandrogens (ADT), which inhibit the expression of AR signaling pathways, one of the principal drivers of PCa progression and EGFR inhibitors, respectively." (PMID 36135315, 2022). "For patients with driver mutations, such as EGFR (10% of NSCLC cases) and BRAF (0.5–4.9% of lung adenocarcinomas), and rearrangements in ROS1 (1–2% of lung adenocarcinomas) and ALK (3–7% of lung adenocarcinomas) gene-targeted therapy can be used." (PMID 35216378, 2022). "For the advanced NSCLC, the value of thoracic radiotherapy in the patients with EGFR mutant lung adenocarcinoma for the OS of patients has been previously investigated." (PMID 36153486, 2022). "Despite manufacturers’ recommendations to avoid gefitinib or erlotinib with PPIs or H2RAs, 25% of patients with EGFR-mutant advanced lung adenocarcinoma were administered AS concurrent with first-line TKIs." (PMID 35488047, 2022). "This is a relatively new finding that the SNP of GAS5 can grossly affect the clinicopathological characteristics of lung adenocarcinoma with wild-type EGFR." (PMID 36011604, 2022). "CM from CAFs increased the resistance of EGFR mutant lung adenocarcinoma cell line PC-9 cells to EGFR-TKI, indicating that the secretion of higher amounts of HGF is the robust feature of EGFR-TKI-resistance-promoting CAFs." (PMID 35326670, 2022). "For example, there is increased expression of the integrin β1 subunit in lung adenocarcinoma cells relative to normal lung epithelium, where it promotes EGFR signaling and tumorigenesis." (PMID 35763345, 2022). "The delicate particulate matter in the polluted air significantly reduced the cell survival rate of the EGFR mutant (19-del) human lung adenocarcinoma cell lines HCC827." (PMID 35606799, 2022). "In advanced lung adenocarcinoma treated with first-generation EGFR-TKIs, elevated SIRI was correlated with worse ECOG PS, EGFR 19-Del mutation, OS and PFS, SIRI was an independent survival predictor." (PMID 35186740, 2022). "We also found that the presence of driver mutation in EGFR was associated with higher MATH score, which is consistent with a previous study based on multi-region sequencing showing high intra-tumor heterogeneity in EGFR-mutant lung adenocarcinoma." (PMID 35847947, 2022). "Due to the limited role of TSC2 in lung adenocarcinoma, EGFR should be able to regulate mTOR activity in other ways." (PMID 35090513, 2022). "In a recent study carried out by Li and co-workers, it was reported that ERCC1 overexpression inhibited the activation of the EGFR and stimulated resistance in lung adenocarcinoma cells to the combined therapy of cetuximab and cisplatin." (PMID 36558926, 2022). "The aim of this study is to investigate the relationship between Ki67 expression as well as epidermal growth factor receptor (EGFR) mutation and the risk of recurrence in postoperative patients with stage I lung adenocarcinoma." (PMID 36617471, 2022). "This case report provides treatment strategies for epidermal growth factor receptor tyrosine kinase inhibitors (EGFR-TKIs)-untreated lung adenocarcinoma patients simultaneously carrying MET alterations and EGFR exon 20 insertion mutations." (PMID 35739536, 2022).
lung adenocarcinoma (continued). "While the epidermal growth factor receptor (EGFR) is an important target for lung adenocarcinoma (LUAD) therapy, acquired resistance is still inevitable." (PMID 36291859, 2022). "Of note, oncogenic EGFR is found in approximately 15% of lung adenocarcinomas and several other cancer types." (PMID 35269796, 2022). "The aim of the present study was to examine ERα, ERβ and GPER1 expressions, and to evaluate their correlation with clinicopathologic factors and with the frequency of EGFR and KRAS gene mutations in lung adenocarcinoma." (PMID 35664735, 2022). "In our own previous clinical results, we found that high PHLPP expression predicted longer duration of acquired resistance in lung adenocarcinoma patients with EGFR tyrosine kinase inhibitors." (PMID 34168988, 2021). "The mutual exclusivity of EGFR amplification and KRAS mutations has been described in lung adenocarcinoma and colorectal carcinoma (CRC) and co-expression caused cytotoxic effect on cells." (PMID 34285259, 2021). "The stacking model showed the potential to help clinicians making decision automatically and non-invasively by identifying suitable advanced patients with lung adenocarcinoma for EGFR‐TKI therapy." (PMID 34367993, 2021). "We only enrolled patients receiving EGFR-TKIs with intraoperatively-confirmed occult M1a lung adenocarcinoma, who have been hospitalized in the department of thoracic surgery." (PMID 33954108, 2021). "The two most common EGFR-activating mutations in NSCLC are in-frame deletions in exon 19 and the L858R point mutation in exon 21, accounting for 45% and 40–45% of lung adenocarcinoma patients, respectively." (PMID 33562150, 2021). "We also found that that the TSHZ2 expression was negatively correlated with the EGFR expression in most lung adenocarcinoma cell lines." (PMID 33850468, 2021). "Somatic EGFR mutation rate in our study was 51.6%, similar to the 50.2% reported by the PIONEER study of Chinese patients with lung adenocarcinoma." (PMID 34869019, 2021). "It was expected that c-Src inactivation was attained by dasatinib in the EGFR-mutant lung adenocarcinoma cells." (PMID 34367939, 2021). "Patients with high YAP expression tended to have high p62 expression, supporting our previous experimental conclusion that YAP regulates p62 expression in EGFR‐mutant lung adenocarcinoma." (PMID 33486901, 2021). "Targeting the epidermal growth factor receptor (EGFR) with tyrosine kinase inhibitors (TKIs) is one of the major precision medicine treatment options for lung adenocarcinoma." (PMID 34622577, 2021). "Further prospective studies are warranted, with a larger number of patients, which focus on lung adenocarcinoma with BM and treatment with EGFR-TKIs." (PMID 34577890, 2021). "The aim of this study was to evaluate immunohistochemistry’s performance in detecting the E746-A750 deletion in exon 19 of the EGFR gene in primary lung adenocarcinoma cases." (PMID 34181354, 2021). "Lung adenocarcinoma consists of lots of therapy targets, and the EGFR Tyrosin Kinase related Inhibitors (TKIs) have been widely and effectively applied in clinical treatments for a decade, shortening the suffering process." (PMID 34656164, 2021). "Patients with EGFR-mutant lung adenocarcinomas have a 70% response rate to first-line EGFR-TKI therapy, such as erlotinib, gefitinib, or afatinib." (PMID 34439273, 2021). "This retrospective study aimed to evaluate the difference in efficacy of these radiotherapy modes in patients with EGFR-mutant lung adenocarcinoma with BMs." (PMID 34847914, 2021). "Expression of either RIT1M90I or KRASG12V in PC9 EGFR-mutant lung adenocarcinoma cells renders them resistant to the EGFR inhibitors erlotinib or osimertinib, conferring an almost 1000-fold decrease in drug sensitivity." (PMID 34373451, 2021).
lung adenocarcinoma (continued). "We found a high heterogeneity of EGFR driver genes between tumors in patients with multiple primary lung adenocarcinoma, suggesting the importance of EGFR testing in the diagnosis of such patients." (PMID 35096585, 2021). "Gene 33 knockdown renders EGFR-TKI-resistant PC9/GR lung adenocarcinoma cells sensitive to EGFR-TKI inhibition." (PMID 34206547, 2021). "But our experimental data indicated that even though ERK signaling is activated in EGFR‐mutant lung adenocarcinoma such as PC9 cells, overexpression of YAP can induce ERK signaling even more." (PMID 33486901, 2021). "there are no previous reports of upfront combination therapy with immunotherapy and chemotherapy for lung adenocarcinoma with brain metastasis harboring EGFR 20 insertion." (PMID 34398022, 2021). "After phase I trials confirmed activity of afatinib in EGFR mutation-positive NSCLC, the phase II LUX-Lung 2 trial assessed the efficacy of afatinib in patients with lung adenocarcinoma with activating EGFR mutations (exon 18–21)." (PMID 33671873, 2021). "744/805 EGFR cases and 3096/4915 other cases were lung adenocarcinoma (Chi-squared test statistic was 2755511, p-value <10-6)." (PMID 34055528, 2021). "The overexpression of SIPR3 increased the EGFR expression in lung adenocarcinoma cell lines and SIPR3 knockout abrogates S1P-dependent EGFR activation." (PMID 33920887, 2021). "Plasma samples of 43 advanced EGFR T790M-positive lung adenocarcinoma patients were collected pre-osimertinib and at the time of progression under osimertinib." (PMID 33919291, 2021). "In the study, we found that patients with age ≥ 66 years and Foxplow TILs were independent prognostic factors for DFS in EGFR-mutant lung adenocarcinoma." (PMID 34484468, 2021). "This ADC showed significant in vivo antitumor activity against EGFR-positive lung adenocarcinoma cells." (PMID 35602228, 2021). "We also found that the EGFR wild type lung adenocarcinomas had significantly more gain at 9q, an aberration difference not described earlier." (PMID 34625038, 2021). "In one of these studies, which involved 93 patients with EGFR‐mutant lung adenocarcinoma, patients with T790M (n = 58, 62%) had better post‐progression survival (median survival, 19 vs. 12 months; p = 0.036) than T790M‐negative patients." (PMID 33529490, 2021). "In lung adenocarcinoma, several resistance mechanisms of EGFR-targeted drugs such as erlotinib and osimertinib (EGFR-targeted small-molecule inhibitors) have been well established." (PMID 34207383, 2021). "GGA2 gene has been identified as a cooperative driver of EGFR-mediated lung adenocarcinoma, and GGA2 protein has been reported to be upregulated in HCC and CRC." (PMID 34799560, 2021). "We found that age ≥ 66 years (age < 66 years; HR = 1.169; 95% CI,1.112–1.877; P = 0.009) and Foxplow TILs (Foxphigh TILs; HR = 0.711; 95% CI, 0.381–1.101; P = 0.017) were independent prognostic factors for DFS in EGFR-mutant lung adenocarcinoma." (PMID 34484468, 2021). "Intratumoral epidermal growth factor receptor (EGFR) mutation status has been especially found to be a strong predictive factor in lung adenocarcinomas (AC) for the efficacy of EGFR-tyrosine kinase inhibitors (TKI)." (PMID 32876329, 2021). "The AURA3 study showed that osimertinib, a third‐generation EGFR TKI, is effective as a second‐line treatment for T790M mutation‐positive lung adenocarcinomas." (PMID 33586356, 2021). "c-Src inactivation through dasatinib was able to seal the survival-signaling-related phosphotyrosines of EGFR to increase the TKIs-induced necroptosis in the EGFR-mutant lung adenocarcinoma." (PMID 34367939, 2021). "The present study showed that in patients with EGFR-mutant lung adenocarcinoma with BM, local radiotherapy and WBRT + Boost perform similarly well both in the subgroups with low and high scores of Lung-molGPA." (PMID 34847914, 2021). "The weakest ability of RESV to induce caspase-3 was noticed for EGFR-mutant lung adenocarcinoma HCC827 cells." (PMID 33652978, 2021).
lung adenocarcinoma (continued). "Accordingly, intrinsic apoptosis was highly variable in the TKI-induced cell deaths of EGFR-mutant lung adenocarcinoma." (PMID 34367939, 2021). "Tyrosine kinase inhibitors (TKIs) suppress EGFR-related signaling to yield cell deaths of lung adenocarcinoma by both necroptosis and intrinsic apoptosis." (PMID 34367939, 2021). "Cbl Proto-Oncogene C (CBLC) was demonstrated to enhance epidermal growth factor receptor dysregulation and signaling in lung adenocarcinoma." (PMID 34722520, 2021). "The addition of dasatinib in the EGFR-mutant lung adenocarcinoma cells efficiently attenuated c-Src activation." (PMID 34367939, 2021). "The Kristen rat sarcoma virus (KRAS) and epidermal growth factor receptor (EGFR) are often overexpressed in women's lung adenocarcinoma." (PMID 34079807, 2021). "The EGFR-mutant lung adenocarcinomas had specific arm-wise aberrations particularly at chromosome7p and 9q." (PMID 34625038, 2021). "With the advent of potent EGFR tyrosine kinase inhibitors (TKIs), the treatment landscape of EGFR-mutant lung adenocarcinomas has changed drastically in recent years." (PMID 34572868, 2021). "Caspase-9 inhibitor and nec-1 were able to prevent tumor cells from apoptosis and necroptosis, respectively, in the EGFR-mutant lung adenocarcinoma cells." (PMID 34367939, 2021). "In our study, we investigated lung adenocarcinoma patients with occult pleural disseminations receiving EGFR-TKIs and found out upfront primary tumor resection was associated with improved survival." (PMID 33954108, 2021). "Here, we found that WWOX SNPs exhibited significant associations with the size of the primary tumor and the invasion of adjacent tissues in patients with EGFR mutant lung adenocarcinoma, especially those with EGFR-L858R mutant." (PMID 34948746, 2021). "In conclusion, we provide evidence of possible global inhibition of HLA peptide processing and presentation upon osimertinib resistance in EGFR mutant lung adenocarcinoma." (PMID 34638461, 2021). "This study aims to determine hub genes related to the incidence and prognosis of EGFR-mutant (MT) lung adenocarcinoma (LUAD) with weighted gene coexpression network analysis (WGCNA)." (PMID 34868228, 2021). "A 62-year-old male with NSCLC (Patient 2, Treat3 & Control3) (left lung adenocarcinoma, EGFR exon 19 deletion) was treated with gefitinib." (PMID 34391435, 2021). "First-generation EGFR-TKIs combined with chemotherapy was reported to be more effective than TKIs alone in advanced lung adenocarcinoma patients." (PMID 34485120, 2021). "TKIs had the great efficacy to inhibit the phosphorylation of tyrosine 1068, 1086, and 1145 of EGFR in the EGFR-mutant lung adenocarcinoma cells." (PMID 34367939, 2021). "In summary, this study uncovered a previously uncharacterized interaction of EGFR with HDAC1 in lung adenocarcinoma cell lines." (PMID 33976119, 2021). "In this study, we conducted clinical oncological investigation on the potential role of DNA methylation in mediating IR to EGFR-TKI treatment in patients with advanced lung adenocarcinoma." (PMID 34036228, 2021). "DUSP6 was upregulated in EGFR- or KRAS-mutant lung adenocarcinoma cells with high ERK phosphorylation levels, which enables tumor cell growth by suppressing hyperactive ERK." (PMID 34685488, 2021). "We conducted genome-wide DNA methylation profiling of 79 tumors sampled from patients with advanced lung adenocarcinoma before they received EGFR-TKI treatment and analyzed the patient responses." (PMID 34036228, 2021). "In Ontario, testing for predictive biomarkers including EGFR for lung adenocarcinoma, BRAF in malignant melanoma and KRAS and BRAF in metastatic colorectal cancer supports the use of targeted therapies for these patients." (PMID 34597339, 2021). "All patients were diagnosed with stage IV EGFR-mutant lung adenocarcinoma and received TKI as first-line treatment." (PMID 34676174, 2021).